FUT7 (fucosyltransferase 7)
Description:
Catalyzes the transfer of L-fucose, from a guanosine diphosphate-beta-L-fucose, to the N-acetyl glucosamine (GlcNAc) of a distal alpha2,3 sialylated lactosamine unit of a glycoprotein or a glycolipid-linked sialopolylactosamines chain through an alpha-1,3 glycosidic linkage and participates in the final fucosylation step in the biosynthesis of the sialyl Lewis X (sLe(x)), a carbohydrate involved in cell and matrix adhesion during leukocyte trafficking and fertilization. In vitro, also synthesizes sialyl-dimeric-Lex structures, from VIM-2 structures and both di-fucosylated and trifucosylated structures from mono-fucosylated precursors. However does not catalyze alpha 1-3 fucosylation when an internal alpha 1-3 fucosylation is present in polylactosamine chain and the fucosylation rate of the internal GlcNAc residues is reduced once fucose has been added to the distal GlcNAc. Also catalyzes the transfer of a fucose from GDP-beta-fucose to the 6-sulfated a(2,3)sialylated substrate to produce 6-sulfo sLex mediating significant L-selectin-dependent cell adhesion. Through sialyl-Lewis(x) biosynthesis, can control SELE- and SELP-mediated cell adhesion with leukocytes and allows leukocytes tethering and rolling along the endothelial tissue thereby enabling the leukocytes to accumulate at a site of inflammation. May enhance embryo implantation through sialyl Lewis X (sLeX)-mediated adhesion of embryo cells to endometrium. May affect insulin signaling by up-regulating the phosphorylation and expression of some signaling molecules involved in the insulin-signaling pathway through SLe(x) which is present on the glycans of the INSRR alpha subunit.
Synonyms: FucT-VII
Tractability: Small molecule: a high-quality ligand is known. Antibody: UniProt predicts a signal peptide or a membrane-spanning region. PROTAC: ubiquitination databases record sites on it; a small molecule that binds it is known.
Target class: Enzyme; Transferase
Gene: Protein-coding gene on chromosome 9 (137,030,174 to 137,032,825, reverse strand). Ensembl gene ENSG00000180549.
Subcellular location: Golgi apparatus, Golgi stack membrane
Subcellular location (Human Protein Atlas): Golgi apparatus
Pathways (Reactome):
Metabolism: Lewis blood group biosynthesis
Gene Ontology:
Molecular function: 4-galactosyl-N-acetylglucosaminide 3-alpha-L-fucosyltransferase activity; alpha-(1->3)-fucosyltransferase activity; fucosyltransferase activity; protein binding
Biological process: ceramide metabolic process; embryo implantation; glycoprotein biosynthetic process; positive regulation of cell adhesion; positive regulation of cell-cell adhesion; positive regulation of leukocyte adhesion to vascular endothelial cell; regulation of cell adhesion molecule production; regulation of cell-cell adhesion; regulation of insulin receptor signaling pathway; regulation of leukocyte cell-cell adhesion; regulation of leukocyte tethering or rolling; inflammatory response; L-fucose catabolic process; leukocyte migration involved in inflammatory response; lymphocyte migration into lymph node; oligosaccharide biosynthetic process; positive regulation of leukocyte tethering or rolling; positive regulation of neutrophil migration; regulation of type IV hypersensitivity; sphingolipid metabolic process
Cellular component: Golgi apparatus; membrane; trans-Golgi network; Golgi membrane; Golgi cisterna membrane
Genetic constraint (gnomAD): Loss-of-function variants: 4 observed, 7.67 expected, observed/expected ratio (o/e) 0.52, 90% interval 0.26 to 1.19. That is too few expected variants to judge how well the gene tolerates losing a copy. Missense variants: 461 observed, 456.44 expected, observed/expected ratio (o/e) 1.01, 90% interval 0.94 to 1.09. Synonymous variants: 218 observed, 193.55 expected, observed/expected ratio (o/e) 1.13, 90% interval 1.01 to 1.26.
Homologues: Orthologues: chimpanzee FUT7 (99% identical), macaque FUT7 (95% identical), guinea pig FUT7 (82% identical), pig FUT7 (82% identical), rat Fut7 (80% identical), dog FUT7 (80% identical), mouse Fut7 (80% identical), Caenorhabditis elegans fut-4 (27% identical), Caenorhabditis elegans fut-1 (27% identical), Caenorhabditis elegans fut-3 (25% identical), Caenorhabditis elegans fut-5 (25% identical), Drosophila melanogaster FucTD (22% identical), and 8 more. Paralogues in human: FUT4 (46% identical), FUT5 (42% identical), FUT6 (41% identical), FUT3 (40% identical), FUT9 (37% identical), POFUT3 (26% identical), POFUT4 (24% identical).
Diseases named in the same sentence as FUT7 in open-access papers:
FUT7 is named in the same sentence as 35 diseases in open-access papers, as found by Europe PMC text mining. Sharing a sentence is not in itself a finding about the gene and the disease. The quoted sentences say what the papers report.
breast carcinoma (6 papers, 2017 to 2024). "In other reports, the main α1,3/4‐FUTs associated with sLeX biosynthesis in breast cancer included FUT3, FUT6, and FUT7." (PMID 29215790, 2018). "Eight loci (PABPC4L, APBA2, FAM189A1, FUT7, ENTPD2, NPDC1, C9orf139 and L1CAM) were associated with risks for both breast cancer and ovarian cancer (P<0.05)." (PMID 28145423, 2017). "In addition, in silico analyses showed that the mRNA levels of fucosyltransferase genes FUT2, FUT3, and FUT7 also upregulated in breast cancer tissues compared with the adjacent noncancerous breast tissues in 113 pairs of breast cancer from the TCGA database." (PMID 33976130, 2021).
lung carcinoma (6 papers, 2015 to 2023). "Expression of FUT7 is related to poor prognosis in lung cancer and sLeX over-expression is associated with tumor metastasis, recurrence, and overall survival in patients with cancer." (PMID 33963380, 2021). "Evidence is mounting that the expression of FUT7 is increased in liver cancer, lung cancer, breast cancer and other solid tumors." (PMID 36463240, 2022). "The purpose of our study is to explore the relationship of lung cancer with FUT7 methylation in peripheral blood and the detection value of FUT7 methylation in LC patients." (PMID 36463240, 2022). "In vitro studies in A549 lung cancer cell lines have shown that FUT7 overexpression augments sLeX synthesis to trigger cell proliferation via the activation of the EGFR/AKT/mTOR signaling pathway." (PMID 33963380, 2021). "Knockdown of FUT4/CD15 and FUT7/CD15s significantly reduced the number of adherent metastatic and primary lung cancer cells as well as GBM cells to brain endothelium." (PMID 31104223, 2019). "Reduced levels of FUT7 CpG DNA methylation have been found in lung cancer, especially in LUSC, and FUT7 promotes lung cancer proliferation by activation of the EGFR/AKT/mTOR signal pathway." (PMID 37256139, 2023).
bladder cancer (4 papers, 2022 to 2025). "A recent study further confirmed that FUT7 expression is elevated in bladder cancer tissues relative to normal tissues and is associated with poor prognosis." (PMID 40252176, 2025). "This upregulation was validated through immunohistochemical analysis and ELISA-based detection of FUT7 in the serum of bladder cancer patients, reinforcing its potential as a biomarker for bladder cancer detection." (PMID 40252176, 2025). "Bladder cancer cell lines engineered to overexpress FUT7 exhibited significantly increased proliferation, migration, and invasion capabilities, accompanied by an induction of EMT." (PMID 40252176, 2025). "Ultimately, strategies involving ST3GAL5 and ST8SIA1 overexpression, or inhibition of ST3GAL6, FUT4 and FUT7, could offer new therapeutic avenues for bladder cancer." (PMID 40252176, 2025). "The methylation level of FUT7 was decreased in bladder cancer tissues and reduced in patients with high stage status and nodal metastasis, indicating that FUT7 methylation level might be a potential indicator reflecting clinical features of bladder urothelial carcinoma." (PMID 36463240, 2022). "FUT7 promoted the proliferation, migration, invasion, and EMT of bladder cancer cells, and positively correlated with immune cell infiltration levels (CD8+ T cells, CD4+T cells, macrophage, neutrophil, and DCs)." (PMID 35784355, 2022). "Moreover, fucosyltransferase 7 (FUT-7) expression was positively correlated with the number of tumor-infiltrating lymphocytes, tumor cell proliferation, migration, and invasion rate, as well as occurrence of epithelial-mesenchymal transition (EMT) in bladder cancer cells." (PMID 36430846, 2022).
follicular thyroid carcinoma (4 papers, 2021 to 2022). "FUT7 is observed to be abnormally expressed in various cancers and could mediate the malignant behavior change in bladder urothelial carcinoma and follicular thyroid carcinoma." (PMID 35444644, 2022).
bladder urothelial carcinoma (3 papers, 2022). "FUT7 is induced by L-selectin to facilitate hematogenous carcinoma metastasis, which is supported by aggregated platelets and white blood cells, while in bladder urothelial carcinoma it is associated with epithelial–mesenchymal transition." (PMID 35625673, 2022).
colitis (3 papers, 2013 to 2025). Inflammation of the colon. "The deletion of FUT7 was shown to reduce the recruitment of leukocytes and the severity of dextran sulphate sodium-induced colitis, mainly by regulating the combination of selectins and their ligands." (PMID 40821120, 2025). "Furthermore, Treg-specific Fut7 knockout decreased colonic Tregs and aggravated the severity of colitis and IEC barrier disruption in the 2,4,6-trinitrobenzenesulfonic acid-induced mouse CD model, while upregulation of Fut7 in Tregs alleviated their severity." (PMID 41398516, 2025). "Furthermore, FUT7 participated in immune regulation in colitis." (PMID 40821120, 2025). "On top of this model, transfer of Tregs in vivo ameliorated colitis and IEC barrier disruption in the naive CD4+ T cell transfer model, but Fut7-knockdown Tregs cannot do so." (PMID 41398516, 2025).
colon cancer (3 papers, 2014 to 2022). "Previous study indicates that NEU4 desialylates cell surface sLeA/X to LeA/X without affecting the expression of ST3GAL3, ST3GAL4, FUT3, and FUT7 in colon cancer cells." (PMID 34135905, 2021). "AQP1, a Colton blood group antigen system gene, was reported to be associated with poor prognosis in colon cancer and lung adenocarcinoma, while seven of the fifteen genes were reported to be prognostic in one tumor type (GCNT2, FUT7, FUT3, FUT2, DARC, CR1 and BSG)." (PMID 35955933, 2022). "In colon cancer SW488 cells, hypoxia induces expression of FUT7 and ST3GAL1, leading to overexpression of sialyl Lewis X antigen and hematogenous metastasis to liver via E-selectin." (PMID 24753248, 2014).
leukemia (3 papers, 2023 to 2024). A malignant (clonal) hematologic disorder, involving hematopoietic stem cells and characterized by the presence of primitive or atypical myeloid or lymphoid cells in the bone marrow and the blood. "Hence, this data indicates that FUT7-mediated upregulation of sLeX on the NK cells can help them better infiltrate leukemia-containing E-selectin high BM compartments and thereby partially overcome the poor infiltration observed for unmodified NK cells." (PMID 38182818, 2024). "FUT7 is a leukocyte-specific FUT and was accordingly only found in the two leukemia cell lines EOL-1 and Molm13 from the sLeX-positive subset." (PMID 37486674, 2023). "The two leukemia cell lines from the sLeX-positive subset where the only ones with convincing FUT7 expression but lacked FUT3." (PMID 37486674, 2023).
melanoma (3 papers, 2021 to 2024). A malignant, usually aggressive tumor composed of atypical, neoplastic melanocytes. "Thus, elevated FUT7 expression has a well-established role in metastasis and we show here for the first time that elevated Fut7 expression can promote the spontaneous metastasis of melanoma cells." (PMID 33963380, 2021).
glioma (2 papers, 2020 to 2021). A benign or malignant brain and spinal cord tumor that arises from glial cells (astrocytes, oligodendrocytes, ependymal cells). "High-grade glioma cells showed overexpression of several sialyl- and fucosyltransferases involved in the biosynthesis of Lewis glycans and the high expression of SLex could be attributed to the expression of FUT7/11 and ST3GAL3." (PMID 33447350, 2020).
adult T cell leukemia (1 paper, 2018). "Human T-lymphotropic virus 1 (HTLV 1) retrovirus, the etiologic agent of adult T cell leukemia, encodes a transcriptional activator protein (TAX) which regulates the FUT7 gene that encodes FucT-VII, the limiting enzyme controlling SLex synthesis in leukocytes." (PMID 30237983, 2018).
B cell lymphoma (1 paper, 2022). "In the current study, we discovered that in clinical B cell lymphoma FUT7 responsible for creating sLeX was highly expressed on NK cells and CLA that presented sLeX was positively correlated with the accumulation of NK cells in tumor bed." (PMID 35784355, 2022).
endometrial endometrioid carcinoma (1 paper, 2020). "The gene expression of FUT7 and FUT8 was significantly increased in endometrial endometrioid carcinoma tissues, compared to those of the normal endometrium (P < 0.05)." (PMID 32099910, 2020).
hepatocellular carcinoma (1 paper, 2021). A malignant tumor that arises from hepatocytes. "FUT7 expression is up-regulated at both mRNA and protein levels in hepatocellular carcinoma HepG2 cells, and an sLex-binding DNA aptamer effectively inhibited the interactions between E-selectin and sLex in HepG2 cells, resulting in reduced adhesion, migration, and invasion of the cells in vitro." (PMID 33963380, 2021).
meningioma (1 paper, 2024). A generally slow growing tumor attached to the dura mater. "We found that the respective expression of FUT2, FUT3, FUT6, and FUT7 was also increased in the malignant meningiomas—HKBMM and IOMM-Lee." (PMID 38274327, 2024). "High expression of FUT1, FUT2, FUT3, FUT6, FUT7, and FUT8 in malignant meningioma cell lines—HKBMM and IOMM-Lee—may represent a fucosylation signature of mucin-type O-linked glycosylation in malignant meningiomas." (PMID 38274327, 2024). "FUT1, FUT2, FUT3, FUT6, FUT7, and FUT8 were highly increased in malignant meningioma cell lines." (PMID 38274327, 2024).
metastatic cancer (1 paper, 2019). A carcinoma which has spread from the original site of growth to another anatomic site. "Knockdown of FUT4 and FUT7 in metastatic cancer cells prevented disruption of an in vitro BBB model." (PMID 31104223, 2019).
Sepsis (1 paper, 2020). Sepsis is defined as life-threatening organ dysfunction caused by a dysregulated host response to infection. "It is associated with FUT7 and AMPD3 in adult SIRS and sepsis." (PMID 32318053, 2020).
triple-negative breast carcinoma (1 paper, 2023). An invasive breast carcinoma which is negative for expression of estrogen receptor (ER), progesterone receptor (PR), and human epidermal growth factor receptor 2 (HER2). "Additionally, FUT7 might modulate the immune microenvironment of triple negative breast cancer via glycolysis regulation, indicating the role of FUTs in regulation of cell conjunction and metastatic process." (PMID 37946130, 2023).
type 1 diabetes (1 paper, 2021). "FUT7 gene has been demonstrated to be linked with an antigen termed bile salt-dependent lipase which is reported to be associated with type 1 diabetes." (PMID 34295899, 2021).
tumor (15 papers, 2017 to 2025). "FUT7 plays a major role in the migration of tumor cells from blood vessels to the surrounding tissue and was conclusively hypermethylated among our EC patients compared to women with benign changes." (PMID 35284957, 2022). "In bladder cancer, FUT7 expression is correlated with tumor-infiltrating lymphocytes and promotes tumor proliferation, migration, invasion, and EMT." (PMID 34948129, 2021). "Furthermore, FUT7 expression in BC has been shown to correlate positively with the number of tumor-infiltrating lymphocytes, tumor growth and invasiveness, cancer cell migration, and the occurrence of EMT." (PMID 37110670, 2023). "IL4I1, ITGB7, and FUT7, which were identified by comprehensive bioinformatic analysis, may play a vital role in the tumour immune microenvironment and hold the potential of enhancing ICB treatment by remodelling glucose metabolism." (PMID 34134578, 2021). "Focusing on glycosyltransferases expression in tumor tissues, we observed two distinct expression clusters, segregating FUT3, FUT4, FUT6, and ST3GAL4 transcripts, from FUT7, FUT9, ST3GAL3, and ST3GAL6." (PMID 39508360, 2025). "As the genetic drivers and tumor control networks are obviously different in LUAD and LUSC, further research works are needed to explain the specific mechanism for FUT7 methylation in the progress of LUAD and LUSC." (PMID 36463240, 2022). "FUT7 was found to be a GPA and a best predictor of good prognosis in BRCA, despite experimental studies showing its tumor-promoting activity." (PMID 35565254, 2022). "Hence, this data did not clearly indicate that FUT7-modified NK cells have a higher propensity for BM homing compared to controls when infused into tumor-free mice." (PMID 38182818, 2024).
cancer (11 papers, 2019 to 2024). A tumor composed of atypical neoplastic, often pleomorphic cells that invade other tissues. "Briefly, the high expression of seven blood group antigen genes, i.e., FUT7, AQP1, P1, C4A, AQP3, KEL, and DARC, was significantly associated with good prognosis in six types of cancers, i.e., KIRC, HNSC, LUAD, CESC, SARC, MESO." (PMID 35955933, 2022). "In conclusion, IL4I1, ITGB7, and FUT7 were identified as the hub genes between two hallmarks in cancer, glucose metabolism, and cancer-specific immunity via comprehensive bioinformatic analysis." (PMID 34134578, 2021). "Most important, IL4I1, ITGB7, and FUT7 were revealed in both the cancer-immune gene set and glucose metabolic gene set." (PMID 34134578, 2021). "IL4I1, ITGB7, and FUT7 may be the hub genes that link glucose metabolism, and cancer-specific immunity." (PMID 34134578, 2021). "Therefore, it appears that FUT3 (in solid malignancies) and FUT7 (in leukemic cells) represent rate-limiting enzymes of sLeA/X synthesis and could be useful targets to block sLeA/X synthesis in cancer cells." (PMID 37486674, 2023). "The top ten from the univariable analyses for the cancer versus cancer-free comparison composed of two miRNAs (409 and 200c) and 8 CpG sites (4 CpGs at SLC22A18, 3 at HYAL2, and 1 at FUT7)." (PMID 35284957, 2022). "Here, we wanted to further investigate the role of CD15 and CD15s on the potential transmigration of cancer cells across an intact brain endothelial monolayer by modulating CD15 and CD15s expression by targeting the FUT4 and FUT7 genes." (PMID 31104223, 2019). "There were no researches about the roles of FUT7, PADI1, PPL, and ARHGAP40 in LSCC, but the roles of these genes or the related genes in other cancers were reported." (PMID 34131588, 2021).
infection (3 papers, 2010 to 2021). The state of being infected such as from the introduction of a foreign agent such as serum, vaccine, antigenic substance or organism. "Except for the Fut4 that was not significantly altered in the Gcnt1 deficient animals, an up-regulation of the α1,3-fucosyltransferases, Fut7, 9, 10 and 11, was observed upon infection by M. tuberculosis, in line with the data obtained for C57BL/6 mice." (PMID 33406734, 2021).
FUT7 also shares sentences with these, for which no sentence is quoted: lung adenocarcinoma (3 papers); atherosclerosis (2); ovarian carcinoma (2); acute myeloid leukemia (1); brain cancer (1); clear cell renal cell carcinoma (1); colorectal cancer (1); endometriosis (1); lung squamous cell carcinoma (1); malignant meningiomas (1); sickle cell disease (1); skin inflammation (1); squamous cell carcinoma (1).